MINDY2-DT (MINDY2 divergent transcript)
Gene: Long non-coding RNA gene on chromosome 15 (58,760,350 to 58,772,120, reverse strand). Ensembl gene ENSG00000245975.
Gene Ontology:
Biological process: RNA processing
Cellular component: nucleolus